MIR194-2HG (MIR194-2 host gene)
Gene: Long non-coding RNA gene on chromosome 11 (64,888,458 to 64,893,484, reverse strand). Ensembl gene ENSG00000229719.
Gene Ontology:
Biological process: miRNA-mediated post-transcriptional gene silencing
Cellular component: RISC complex